PCDHA7 (protocadherin alpha 7)
Description:
Calcium-dependent cell-adhesion protein involved in cells self-recognition and non-self discrimination. Thereby, it is involved in the establishment and maintenance of specific neuronal connections in the brain.
Synonyms: CNRS4; CNR4; CRNR4; CNRN4; PCDH-ALPHA7
Tractability: Antibody: its Gene Ontology location is reachable by antibodies, with high confidence; UniProt places it where antibodies can reach, with medium confidence; UniProt predicts a signal peptide or a membrane-spanning region.
Gene: Protein-coding gene on chromosome 5 (140,834,248 to 141,012,347, forward strand). Ensembl gene ENSG00000204963.
Subcellular location: Cell membrane
Gene Ontology:
Molecular function: calcium ion binding; cell adhesion molecule binding; identical protein binding
Biological process: cell adhesion; cell-cell recognition; homophilic cell-cell adhesion; nervous system development
Cellular component: plasma membrane; membrane
Genetic constraint (gnomAD): Loss-of-function variants: 36 observed, 55.49 expected, observed/expected ratio (o/e) 0.65, 90% interval 0.5 to 0.86. The upper end of that interval is the gene's LOEUF score, 0.86, which puts it in group 3 of 6, group 1 being the genes least tolerant of losing a copy. Missense variants: 1,151 observed, 1,152.6 expected, observed/expected ratio (o/e) 1, 90% interval 0.95 to 1.05. Synonymous variants: 535 observed, 515.37 expected, observed/expected ratio (o/e) 1.04, 90% interval 0.97 to 1.12.
Homologues: Orthologues: mouse Pcdha7 (85% identical), mouse Pcdha8 (82% identical). Paralogues in human: PCDHA9 (90% identical), PCDHA4 (86% identical), PCDHA3 (84% identical), PCDHA13 (82% identical), PCDHA6 (82% identical), PCDHA1 (82% identical), PCDHA10 (82% identical), PCDHA5 (81% identical), PCDHA8 (81% identical), PCDHA2 (81% identical), PCDHA11 (81% identical), PCDHA12 (80% identical), and 49 more.
Diseases named in the same sentence as PCDHA7 in open-access papers:
PCDHA7 is named in the same sentence as 5 diseases in open-access papers, as found by Europe PMC text mining. Sharing a sentence is not in itself a finding about the gene and the disease. The quoted sentences say what the papers report.
depression (2 papers, 2021 to 2024). "Several TWAS significant genes were also dysregulated in brains of depression cases compared with controls (including PCDHA8, FANCL, TMEM161B-AS1, GMPPB, STAU1, NDUFA2, GPX1 and PCDHA7), implying that genetic variants may contribute to depression risk by regulating gene expression." (PMID 34021117, 2021). "The overlapping eQTL genes between AD and depression (SRA1, MICA, PCDHA8, PCDHA10, PCDHA7, and PCDHA13), were not yet associated with these disorders through proximity analysis nor have an established role in these diseases as of yet." (PMID 38862462, 2024).
PCDHA7 also shares sentences with these, for which no sentence is quoted: Alzheimer disease (1 paper); Autoimmunity (1); cancer (1); infection (1).